CLIC1 (CLIC family member 1)
Diseases named in the same sentence as CLIC1 in open-access papers (continued):
Sharing a sentence is not in itself a finding about the gene and the disease.
serous ovarian tumors (1 paper, 2018). "Specifically, CLIC1 mRNA levels were very low in normal ovarian surface epithelium and fallopian tube epithelium, while levels in high grade serous ovarian tumors were significantly higher." (PMID 30282979, 2018).
tumor (72 papers, 2011 to 2025). "Consistent with our in vitro observations, metformin effectively reduced tumor growth in xenografts from NC and WT-rescued cells but was ineffective in Clic1−/− cells or with the R29A point mutation." (PMID 41276810, 2025). "One such protein, chloride intracellular channel 1 (CLIC1), a 241-amino acid ion channel protein, has been implicated in various cellular pathophysiological activities and tumor progression, including chemoresistance." (PMID 39719600, 2024). "GBM aggressiveness correlates with CLIC1-mediated channel activity, suggesting a potential membrane-associated role for CLIC1 in tumor settings." (PMID 38027011, 2023). "CLIC1 expression has been linked to several malignancies’ poor prognoses and tumor growth, according to reports." (PMID 36727059, 2022). "Previous immunohistochemical studies showed that the expression of CLIC1 in human tumor tissue samples was associated with the clinicopathological features and prognosis of patients." (PMID 29796185, 2018). "While CLIC1 has generally been associated with tumor progression in prior studies, there are some contradictions regarding the role of CLIC4 in tumors." (PMID 30282979, 2018). "In order to investigate the molecular mechanisms underlying the roles of CLIC1 expression in tumor progression and apoptosis, microarrays and a pathway analysis using IPA were performed using CLIC1 siRNA-transfected KYSE70 cells." (PMID 29796185, 2018). "All of these studies showed that the high expression of CLIC1 has important association with tumor invasion, metastasis, and prognosis." (PMID 29147652, 2017). "And CLIC1 associated with tumor stage, immune infiltrate, and prognosis." (PMID 36727059, 2022). "All these results indicate CLIC1 is associated with tumor invasion, migration, metastasis, and tumor immune microenvironment and could be an essential biomarker for diagnosis and therapeutic target." (PMID 36727059, 2022). "And CLIC1 associated with tumor stage, and immune infiltrate." (PMID 36727059, 2022). "CLIC1, a member of this family, is found in the cytoplasm or in internal and plasma membranes, with membrane relocalisation linked to endothelial disfunction, tumour proliferation and metastasis." (PMID 35833483, 2022). "Given the potential role of CLIC1 in tumor metastasis, its effects on cell migration and invasion abilities were examined." (PMID 41200185, 2025). "In recent studies, the role of CLIC1 in regulating tumor cell proliferation and apoptosis has been highlighted." (PMID 40948771, 2025). "Pancreatic cancer cells were found to sense ECM stiffness and activate the Wnt/b-catenin/TCF4 signaling pathway, leading to upregulation of CLIC1 expression, which promotes glycolysis-dependent tumor growth." (PMID 40630951, 2025). "Conversely, Clic1-/- R29A-injected mice showed similar tumor sizes in the brain as WT-injected mice; both treated and untreated conditions were comparable in Clic1-/- R29A-injected brains." (PMID 41276810, 2025). "The overexpression of CLIC1 was closely related to tumor size, TNM classification, pathological grade, lymph node metastasis, and Ki67." (PMID 41142627, 2025). "CLIC1-positive stromal cells’ potential to serve as sources of peritumor vasculogenesis remains unstudied despite their high expression in tumor stroma cells." (PMID 38746686, 2024). "Researchers detected isolated CLIC1-positive cells inside the tumor stroma as well as in between tumor cells." (PMID 38746686, 2024). "Metformin exerts anti-tumor effects in GSCs by inhibiting chloride intracellular channel-1 (CLIC1), a protein known for promoting GSC survival, proliferation, and migration." (PMID 38891882, 2024). "CLIC1, a Chloride intracellular channel, was overexpressed in LUAD and was associated with tumor metastasis, tumor staging, and OS." (PMID 39678513, 2024).
tumor (continued). "Recent microscopic evidence about the shape of stromal CLIC1-positive endothelial cells and how they are arranged into cords and tube-like structures seen in cc RCC strongly suggests that CLIC1 is involved in the formation of blood vessels around the tumor." (PMID 38746686, 2024). "Reducing CLIC1 expression impairs cell proliferation and self-renewal in GBM, while CLIC1-mediated channel activity correlates with tumor aggressiveness." (PMID 38053842, 2023). "Single-cell analysis unveiled that CLIC1 was expressed ubiquitously in tumor cells and tumor microenvironment." (PMID 38027011, 2023). "The dysfunctional expression of chloride intracellular channel 1 (CLIC1), a member of the chloride channel protein family, is related closely to tumor invasion, metastasis, treatment resistance, and prognosis." (PMID 36797245, 2023). "In a similar manner, CLIC1 is upregulated in LUAD and is associated with tumor metastasis and shorter survival." (PMID 37408210, 2023). "From the total number of cases—different tumor types (10.967 samples/10.953 patients)—159 were characterized by CLIC1 alteration." (PMID 36826036, 2023). "Similarly, the chloride intracellular channel-1 (CLIC1) is known to be instrumental for tumor proliferation in several solid tumor including GB and his overexpression on GSCs is inversely associated with patient survival, suggesting CLIC1 to be a potential target and prognostic biomarker." (PMID 38188666, 2023). "The significant function of the CLIC1/NF-κB axis in tumor growth was highlighted by evidence that the pyrrolidine dithiocarbamate, an NF-κB inhibitor, prevents CLIC1-dependent pro-tumor actions." (PMID 37048148, 2023). "ccRCC was classified into four groups (Classes 0–3) based on the percentage of positive tumor cells, with each group including sub-groups defined by CLIC1 expression in the endothelium." (PMID 36497464, 2022). "Based on these findings, we can conclude that CLIC1 is important in angiogenesis, tumor progression, and metastasis in ccRCC." (PMID 36497464, 2022). "In our study, we discovered a high degree of variability in CLIC1 translocation in ccRCC tumor cells." (PMID 36497464, 2022). "CLIC1 co-expression in tumor and endothelial cells stratified ccRCC cases into several subgroups, and this co-expression influences TNM staging parameters." (PMID 36497464, 2022). "In this screening we identified only one GSC culture, derived from GBM39, which expresses very low CLIC1 mRNA content, although retaining malignant tumor features similarly to CLIC1-expressing GSC cultures." (PMID 35135603, 2022). "CLIC1 overexpression in tumor cells has recently been identified as a potential angiogenic factor favoring tumor angiogenesis, invasion, and metastasis." (PMID 36497464, 2022). "Gene expression analysis of several MB patient sample cohorts shows CLIC1 overexpression in the tumor samples compared with control tissues." (PMID 35296518, 2022). "In the present study, the highest CLIC1 expression in tumor cells and intravascular tumor emboli, along with an active angiogenic process demonstrated by tumor blood vessel morphology heterogeneity, was reported for tumor stage III." (PMID 36497464, 2022). "Evidence of a link between CLIC1-positive tumor cells and tumor blood vessel endothelial cells has grown in recent years, but CLIC1 expression in endothelial cells has only been reported on cultured endothelial cells." (PMID 36497464, 2022). "We discovered that CLIC1 was expressed not only by ccRCC tumor cells, but also by endothelial cells lining intratumor and peritumor blood vessels with a shape very suggestive of neo-vessels." (PMID 36497464, 2022). "Analysis of Human Protein Atlas and The Cancer Genome Atlas data related to CLIC1 expression in ccRCC and the tumor endothelium revealed that CLIC1, along with CLIC6, are reported to be expressed in both normal and ccRCC human kidney tissues." (PMID 36497464, 2022).
tumor (continued). "CLIC1-positive tumor blood vessels were found in half of them, with densities ranging from 13 to 67 vessels per microscopic field X20." (PMID 36497464, 2022). "CLIC1 was found at the endothelial level in approximately 65% of cases, and 59% of cases had CLIC1 co-localization in both tumor cells and tumor blood vessel endothelium." (PMID 36497464, 2022). "CLIC1 is heterogeneously expressed in ccRCC tumor cells and tumor blood vessel endothelium, influencing tumor stage and progression, as well as nodal and distance metastatic potential." (PMID 36497464, 2022). "CLIC1 expression in both tumor and endothelial cells mark CLIC1 as a potential dual target for specific antibodies-based therapy, which was proven to be effective in experimental models of ccRCC." (PMID 36497464, 2022). "High CLIC1 expression has been reported in a range of malignant tumours and cardiovascular diseases such as pulmonary hypertension and ischaemic cardiomyopathy." (PMID 35833483, 2022). "In our study, Class 3 ccRCC tumors with the highest CLIC1 expression in tumor cells contained the most CLIC1-positive tumor blood vessels." (PMID 36497464, 2022). "CLIC1 contributes to MB proliferation in vitro, and CLIC1 depletion in MB tumor cell lines significantly reduces tumor cell growth in vivo." (PMID 35296518, 2022). "Tumor cells interact with endothelial cells via chloride intracellular channel protein 1 (CLIC1) micro vesicles transfer, inducing endothelial cell proliferation, migration, and tube formation, according to in vitro studies." (PMID 36497464, 2022). "Survival analysis was based on low versus high CLIC1 mRNA expression in correlation with the tumor stage." (PMID 36497464, 2022). "Specifically, tumor-derived EVs carrying c-Myc blocked miR-556-3p expression by upregulating KCNQ1OT1 to elevate CLIC1 expression, thus activating the PI3K/AKT pathway and accelerating GC cell proliferation, invasion, and migration." (PMID 35260554, 2022). "CLIC1 expression in tumor blood vessels is reported for the first time here, suggesting CLIC1 as a new endothelial marker." (PMID 36497464, 2022). "CLIC1 was found in all three cellular compartments of tumor cells in 24% of cases (nuclear-N, cytoplasm-C, and membrane-M)." (PMID 36497464, 2022). "In malignant disease, CLIC1 appears to be a prospective therapeutic target for both tumor and endothelial cells." (PMID 36497464, 2022). "Based on the preliminary findings from this study, CLIC1′s role as an angiogenic factor in human malignancies should be further investigated in other tumor types and correlated with other prognostic and survival factors." (PMID 36497464, 2022). "The number of ccRCC cases distributed according to the interrelation between pTNM/ccRCC classes and CLIC1 expression in tumor blood vessel endothelium and tumor cells." (PMID 36497464, 2022). "The 5-year survival rate was 57% for tumor stage III cases with high CLIC1 expression compared to a 72% 5-year survival rate in the case of low expressing patients from similar tumor stages (III) (p = 0.031)." (PMID 36497464, 2022). "CLIC1 expression was measured not only in tumor cells (ccRCC-TC), but also in the tumor blood vessel endothelium (CLIC1 microvessel density, ccRCC-TBvsE)." (PMID 36497464, 2022). "CLIC1-positive tumor cells with homogeneous or heterogeneous distribution within the tumor area were found in 87.5% of ccRCC cases." (PMID 36497464, 2022). "As is shown, the percentages from both analyses are mostly overlapping, giving strong evidence of CLIC1 involvement in tumor progression and metastasis." (PMID 36497464, 2022). "Conversely, MAP4K4 depletion decreased PM association of proteins involved in tumor immune evasion (CD155, CD276, and HLA-G), in solute influx regulation (CLIC1, SLCs, and ABCCs) and cell migration (CD155 and CD276)." (PMID 35296518, 2022).
tumor (continued). "For Class 2, CLIC1 expression in tumor blood vessels was significantly inversely correlated with the N parameter from the TNM staging system (p value = 0.004)." (PMID 36497464, 2022). "Significant differences regarding survival were registered between cases with low and high CLIC1 expression, dependent by tumor stage and sex." (PMID 36497464, 2022). "Independently, we reported a group called Class 3, which includes 39% of cases with high CLIC1 expression in both tumor and endothelial cells." (PMID 36497464, 2022). "Class 1 exhibited the fewest cases, but they all expressed CLIC1-positive tumor blood vessels, with densities ranging from 10 to 17 vessels/microscopic field X20." (PMID 36497464, 2022). "Only CLIC1 in its channel form has been shown to have pro-proliferative and angiogenic activity, and specific inhibition of CLIC1 channel halts endothelial injury, tumour angiogenesis and progression and vascular inflammation." (PMID 35833483, 2022). "CD8 expression was reduced in tumor tissues when CLIC1 was highly expressed but high when CLIC1 was expressed low." (PMID 36727059, 2022). "CLIC1 nuclear translocation is responsible for the increase in the malignant phenotype in tumor cells, in some cases." (PMID 36497464, 2022). "The current study was conducted solely on human tumor specimens obtained from patients with ccRCC malignancy, and it is the first to report CLIC1 expression in human endothelial cells." (PMID 36497464, 2022). "CLIC1-NMC-positive tumor emboli inside blood vessels with a CLIC1-positive endothelium have been observed far from the tumor in the subcapsular area." (PMID 36497464, 2022). "Although the role of CLIC1 protein in tumorigenesis is still unclear, in recent years, different studies have elucidated the possible involvement of CLIC1 in tumor formation and progression." (PMID 34357102, 2021). "CLIC1 overexpression was shown to be correlated with the three clinical parameters: advanced tumor grade, advanced tumor stage and large tumor size." (PMID 33178018, 2020). "For example, GSCs secrete exosomes carrying chloride intracellular channel protein 1 (CLIC1), which affects tumor proliferation both in vivo and in vitro." (PMID 33059744, 2020). "The relevance of CLIC1 in tumor biology, and for GBM in particular, is further supported by the observation that tmCLIC1 is highly expressed in patient-derived GSC sub-populations." (PMID 30918838, 2019). "If these premises are confirmed, a selective CLIC1 inhibitor should have high efficacy against tumor cells and low toxicity on the normal cell counterparts." (PMID 30918838, 2019). "In the last years, growing evidence highlighted the role of CLIC1 as key factor in tumor development and progression." (PMID 30918838, 2019). "CLIC1 is involved in several physiological cell functions and its abnormal expression triggers tumor development, favoring tumor cell proliferation, invasion, and metastasis." (PMID 30918838, 2019). "The findings show how the chloride channel helps protect tumor cells from surges in calcium and free radicals, and highlight the therapeutic potential of targeting CLIC1 to slow tumor growth." (PMID 31316050, 2019). "As expected from the tumor selective CLIC1 activity, metformin effects on chloride influx and cell division occurred only in GSCs, but not in human umbilical cord mesenchymal stem cells (ucMSC)." (PMID 30186163, 2018). "In this study, a key finding is that at the tissue level either CLIC1 or CLIC4 stained larger percentages of the EOC tumor cores, across all major EOC subtypes, compared to CA125." (PMID 30282979, 2018). "In this process, CLIC1 would contribute to the formation of invadopodia in endothelial and tumor cells, by inducing integrin-mediated actomyosin dynamic." (PMID 30279961, 2018). "The present study provides an insight into the role of CLIC1 as a switch among tumor behaviors in ESCC." (PMID 29796185, 2018).
tumor (continued). "Although further investigations on the underlying molecular mechanisms are needed, the present results suggest that CLIC1 is a useful biomarker of tumor progression and/or a novel therapeutic target for the future treatment of ESCC." (PMID 29796185, 2018). "Consistent with broad staining across nearly all EOC tumor cores, CLIC1 and CLIC4 were also shed more consistently and at higher levels from fresh human tumors across tumor subtypes than CA125." (PMID 30282979, 2018). "In short, our results indicate that CLIC1 expression levels are related to the switching of the tumor behaviors of ESCC." (PMID 29796185, 2018). "In vivo and in vitro proliferation of GBM cancer stem cells depends on CLIC1 activity, and its inhibition reduces tumor development in animal models." (PMID 29147652, 2017). "One of the possible mechanisms by which CLIC1 mediates invasion is by regulating maspin (tumor suppressor), matrix metalloproteinases, annexin A7, and gelsolin." (PMID 26881024, 2016). "Xenograft experiment in nude mice demonstrates that CLIC1 knockdown significantly inhibits tumor growth of A2780, providing further evidence to demonstrate that CLIC1 accelerates cancer cell progression." (PMID 27825122, 2016). "In recent years, studies show CLIC1 was up regulated mainly in digestive system neoplasm, and its high expression is a poor prognosis for diverse tumor patients." (PMID 27825122, 2016). "All of these results suggest that CLIC1 promotes cell malignant transformation and tumor cell proliferation or migration, suggesting it can be a therapeutic target." (PMID 27825122, 2016). "The mean tumor weights were significantly higher in mice bearing tumors derived from U87 cells treated with CLIC1 FLAG EVs." (PMID 26429879, 2015). "Furthermore, the upregulation of CLIC1 exhibited a significant correlation with clinical and pathological stage, tumor size, and overall survival." (PMID 40948771, 2025). "Furthermore, CLIC1-positive tumor cells appear to have a high invasive and metastasis potential in vitro, but data on human tumor tissues are extremely scarce." (PMID 36497464, 2022). "The Class 3 subgroup of cases had the greatest number of CLIC1-positive tumor blood vessels." (PMID 36497464, 2022). "Based on previous findings of CLIC1 co-expression heterogeneity in tumor and endothelial cells, we decided to investigate whether there are any correlations between this expression and the p TNM parameters." (PMID 36497464, 2022). "The role of CLIC1 in tumor progression and metastasis is well established." (PMID 36497464, 2022). "CLIC1 expression in tumor blood vessel endothelium was present in more than half of the cases (59%), and the majority of them (39%) were classified as class 3 due to high levels of CLIC1 expression in the tumor cells." (PMID 36497464, 2022). "Our research previously evaluated chloride intracellular channel 1 (CLIC1) in ccRCC, indicating that it may stratify ccRCC based on its expression pattern, as well as its differential expression in relation to tumor grade." (PMID 36497464, 2022). "Based on this, this research was conducted to figure out whether tumor-derived EVs delivered c-Myc to manipulate KCNQ1OT1/miR-556-3p/CLIC1 axis to affect GC development." (PMID 35260554, 2022). "CLIC1 inhibition may have a synergistic effect on tumor cells, as well as tumor vasculature, as our team previously reported for a ccRCC patient-derived tumor xenograft implanted on a chick embryo chorioallantoic membrane treated with anti-CLIC1 antibodies." (PMID 36497464, 2022). "CLIC1 was found to be expressed, not only in ccRCC tumor cells, but also in tumor blood vessel endothelial cells, suggesting that it could be used as a new potential endothelial marker for tumor angiogenesis assessment." (PMID 36497464, 2022).